EPHA2 (EPH receptor A2)
Diseases named in the same sentence as EPHA2 in open-access papers (continued):
Sharing a sentence is not in itself a finding about the gene and the disease.
cancer (continued). "Upregulation of EphA2 occurs in several cancers such as melanoma, ovarian, prostate, lung, and breast cancer." (PMID 32264958, 2020). "EphA2 overexpression in cancer cells leads to a ligand-independent increase in oncogenic signal transduction." (PMID 33092175, 2020). "We have also observed promising activity for EphA2-ILs-DTXp in combination with immune checkpoint inhibitors in syngeneic cancer models." (PMID 33092175, 2020). "For example, peptide-coated nanoparticles have also been targeted to EphA2 for the delivery of anti-cancer compounds." (PMID 32492868, 2020). "EphA2 belongs to the ephrin-receptor family of receptor tyrosine kinases, and it regulates cancer motility, proliferation, and stemness properties by phosphorylation." (PMID 31936664, 2020). "There is considerable interest in the mechanisms that govern EphA2 expression and in understanding how these mechanisms are subverted in cancer." (PMID 32811512, 2020). "EVs secreted by fibroblasts and senescent epithelial cells bind to ephrin-A1, a molecule highly expressed in several types of cancer cells, and which promotes the proliferation of cancer cells through the reverse signaling of EphA2/ephrine-A1." (PMID 33227947, 2020). "In particular, we focused on EphA2’s potential as a target for cancer treatment to provide insights into the application of EphA2 targeting in anticancer strategies." (PMID 32811512, 2020). "Cleaved by cell matrix metalloproteases, soluble monomeric ephrin-A1 is released from cancer cells and drives EphA2 dimerization and signaling." (PMID 32629797, 2020). "While the absence of antigen escape variants is most likely multifactorial, it is consistent with the central role of EphA2 in maintaining the malignant phenotype of cancer cells." (PMID 33148882, 2020). "A bispecific antibody, targeting both EphA2 and EphA3, has been explored as a potential therapy for glioblastoma, while antibodies targeted to EphB4 have been investigated for anti-cancer activity." (PMID 32492868, 2020). "In contrast, ligand- and tyrosine kinase-independent EphA2 activation (forward signaling) promotes cancer development and progression." (PMID 32848131, 2020). "As for interaction between EphA2 and miR‐26b in cancers, EphA2 was verified as the target of miR‐26b." (PMID 32233022, 2020). "As a result, EphA2 is highly ranked in the NIH’s list for potential cell surface antigen targets for cancer treatment." (PMID 32751634, 2020). "We recently developed a novel EphA2-targeting antibody-directed nanotherapeutic encapsulating a labile prodrug of docetaxel (EphA2-ILs-DTXp) for the treatment of EphA2-expressing malignancies." (PMID 33092175, 2020). "A study on senescent cells identified the transfer of EphA2 to active cancer cells, inducing a signalling cascade via EphA2/ephrin-A1 which resulted in an increased cellular proliferation in the recipient cell, thus promoting a tumorigenic transformation." (PMID 31963599, 2020). "The coexpression of Ephrin-A3 can block the ability of EphA2 and EphA3 to link ephrins in trans and become activated, while Ephrin-B2 can deter not only EphB4 but also EphA3 in the cancer cells." (PMID 32368295, 2020). "The collective results indicated that EphA2 affects several aspects of cancer biology in HuH-7R and Sk-Hep-1 cells." (PMID 32203105, 2020). "Given the positive association of EphA2 overexpression with aggressive clinical and pathological features in human cancers, investigators have examined the potential of downregulating EphA2 in preclinical models." (PMID 32811512, 2020). "Short interfering RNAs (siRNAs) for gene knockdown constitute a great tool for protein function assessment, gene discovery, and drug development, and have been applied to silence EphA2 in human cancer cells." (PMID 32811512, 2020). "A number of studies support important roles of EphA2 in cancer biology, including angiogenesis, tumorigenicity, proliferation, drug resistance, and particularly metastasis." (PMID 32203105, 2020).
cancer (continued). "Consistent with the RSKi results, knockdown of RSK1 and/or RSK2, which are the cancer‐associated RSKs highly expressed in OC cells (Fig EV3A), inhibited the platinum‐induced EphA2‐pS897." (PMID 32115889, 2020). "Immuno-histochemical studies showed EphA2 elevation in cancer epithelia of enzalutamide-treated mice." (PMID 33023262, 2020). "Considered together, the present work has uncovered the oncogenic characteristics of EPHA2 mutations in SSC and MPM reinstating the dynamics of different roles of EPHA2 in cancer." (PMID 31484920, 2019). "It is widely reported that EPHA2 overexpression is correlated with poor prognosis for cancer patients." (PMID 31412935, 2019). "Erythropoietin-producing hepatocellular receptor A2 (EPHA2) is overexpressed on the cell surface in many cancers and predicts poor prognosis." (PMID 31412935, 2019). "EphA2, an erythropoietin-producing hepatocellular (Eph) family member of receptor tyrosine kinases, has long been correlated with the growth of malignant tumors, including gastric cancer." (PMID 30833656, 2019). "The present results suggest that the EPHB6 mutation and its downstream EPHA2/JNK/CDH11/RhoA/FAK signaling axis are novel diagnostic and therapeutic targets for overcoming paclitaxel resistance in cancer patients." (PMID 31160603, 2019). "Ephrin type A receptor (EphA2) is a receptor tyrosine kinase that plays a key role in the development of cancer disease." (PMID 30031396, 2018). "Using hepatic L02 normal cells as a control, the western blot study reveals that EphA2 is predominantly expressed in 4T1 cancer cells." (PMID 29748611, 2018). "Senescent cells secrete more EphA2 and DNA via EVs, which can promote cancer cell proliferation and inflammation, respectively." (PMID 29392820, 2018). "Relevant to cancer, the EphA2-ephrinA1 signaling axis regulates events crucial for cellular transformation and malignancy." (PMID 30222105, 2018). "Overexpression of EphA2 in cancer can promote cancer progression and malignancy, and it is often associated with ephrin downregulation." (PMID 30222105, 2018). "Here the authors show that ROS increase the sorting of EphA2 into extracellular vesicles in senescent cells, which promotes proliferation of cancer cells." (PMID 28585531, 2017). "This initiates EphA2-mediated cell:cell repulsion, thus enabling cancer cells to move away from each other." (PMID 28294115, 2017). "Because membrane type 1-matrix metalloproteinase 1 (MT1-MMP) and erythropoietin-producing hepatocellular receptor 2 (EphA2) expression are upregulated by the Ras/mitogen-activated protein kinase pathway, they are frequently coexpressed in malignant tumors." (PMID 29072678, 2017). "Phase I and II trials are currently being pursued for CAIX, EGFRvIII, PLOD2, and EphA2 targeting chemotherapeutics in different types of cancer." (PMID 29165393, 2017). "Exposure of EphA2-expressing cancer cells to ligand herein revealed a unique role for eHsp90 as an effector of cytoskeletal remodeling." (PMID 29290990, 2017). "The simple incorporation of FFG as a self-assembly-aided unit between AIEgen (TPE-Py) and YSA significantly enhances the fluorescent signal output of TPE-Py when imaging EphA2 clusters in live cancer cells." (PMID 28507673, 2017). "The authors also reported that the malignancy of the cancer cells was correlated to the clustering propensities of EphA2." (PMID 28338017, 2017). "We used this fragment-specific antibody to develop a sandwich enzyme-linked immunosorbent assay (ELISA) and applied it to measure levels of the soluble EphA2 fragment in sera from cancer patients." (PMID 29072678, 2017). "To establish a method for detecting the products of EphA2 processing in cancer patients, we developed mAbs specific to the extracellular domain of EphA2 (antigen #1)." (PMID 29072678, 2017). "Soluble EphA2 fragment levels in cancer-patient sera were higher than those in healthy donors (n=50)." (PMID 29072678, 2017).
cancer (continued). "By virtue of the simple incorporation of FFG as a self-assembly-aided unit, TPE-Py-FFGYSA can image EphA2 clusters in PC-3 cancer cells with a high contrast." (PMID 28507673, 2017). "Cheever and colleagues ranked EphA2 as one of the highest cell surface antigens for cancer treatment." (PMID 28165374, 2017). "In the current study, we developed monoclonal antibodies (mAbs) against the soluble EphA2 fragment released from cancer cells by MT1-MMP cleavage." (PMID 29072678, 2017). "In other cancer types, the co-operation of EphA2 with PI3K/Akt signaling and EPHA4 with FGFR signaling have similarly been shown to promote migration and invasion." (PMID 29101386, 2017). "sEV-associated EphA2 secreted from senescent cells binds to ephrin-A1, that is, highly expressed in several types of cancer cells and promotes cell proliferation through EphA2/ephrin-A1 reverse signalling." (PMID 28585531, 2017). "Higher levels of the soluble EphA2 fragment were observed in cancer patient-derived sera compared with healthy donors." (PMID 29072678, 2017). "In human CRC patients, increased EPHA2 expression levels are positively correlated with cancer progression and liver metastasis." (PMID 29262644, 2017). "TPE-Py-FFGYSA is weakly fluorescent in aqueous solution, and can selectively target EphA2 in PC-3 cancer cells along with its fluorescence turn on." (PMID 28507673, 2017). "In summary, we have reported the synthesis and feasibility of TPE-Py-FFGYSA as an AIE adjuvant that has the combined capabilities of targeted imaging of EphA2 overexpressed in cancer cells and adjuvant amplification of antitumor efficacy of Ptx." (PMID 28507673, 2017). "The Eph receptor tyrosine kinase family member EphA2 plays a pivotal role in modulating cytoskeletal dynamics to control cancer cell motility and invasion." (PMID 29290990, 2017). "As cell:cell repulsion is likely to contribute to cancer cell dissemination, we tested the requirement for EphA2 and RCP in cell scattering." (PMID 28294115, 2017). "The aim of the present study was to further characterize the cross-talk between TF/FVIIa and EphA2 using in vitro model systems and human cancer specimens." (PMID 27246245, 2016). "Even though a large number of studies have confirmed an important role of EphA2 in human cancers, there are controversies regarding the contributions of ligand dependent and ligand independent signaling." (PMID 27246245, 2016). "In summary, we show with a proximity ligation assay and immunofluorescence that TF and EphA2 co-localize in cancer cell lines and that TF/FVIIa cleaves EphA2 in cells with high TF expression in a PAR2-independent manner." (PMID 27246245, 2016). "EPHA2 is highly expressed in aggressive human cancers, and also offers opportunities for Eph/ephrin-based targeted drug delivery and imaging." (PMID 27681698, 2016). "We report herein on a close cross-talk between TF and the tyrosine kinase receptor EphA2 and present evidence of a role for the TF/FVIIa complex as a co-receptor and signaling partner of EphA2 with possible implications in human cancer." (PMID 27246245, 2016). "In support of the relevance of TF/FVIIa-EphA2 cross-talk we present descriptive data that TF and EphA2 were co-expressed to a high extent in a human cancer material, and TF positivity was with a few exceptions only found in EphA2 expressing tumors." (PMID 27246245, 2016). "Although these are distinct cancer types, both TF and EphA2 expression appears to foremost be a feature of advanced cancers, and TF expression is regulated by common oncogenic mutations." (PMID 27246245, 2016). "TF expression was detected in 28 % of primary cancers and 29 % of lymph gland or distant metastases, and EphA2 in 59 % of cases in both groups." (PMID 27246245, 2016).
cancer (continued). "The receptor sub-type EphA2 was identified in cancer cells where it is often highly expressed, mediating communication not only between individual cancer cells, but also between cancer cells and surrounding stromal or vascular cells [6−27]." (PMID 26959746, 2016). "Here we present data on the construction of large, diverse, phage-display and cell-free DNA display libraries and the isolation of high affinity binders to the cancer target, membrane-bound ephrin receptor tyrosine kinase class A2 (EphA2)." (PMID 26313909, 2015). "The level of EphA2 expression has been correlated to disease prognosis and, thus, is a promising target for cancer therapy." (PMID 26313909, 2015). "More recently, the Eph receptors have been investigated as potential targets for cancer therapy, with the most advanced therapies targeting EphA2, EphA3 and EphB4." (PMID 26083390, 2015). "Treatment of trametinib resulted in effective downregulation of the RSK–EphA2 pathway; therefore, it is one possible strategy for intervention of phosphorylation of EphA2 for the treatment of cancers in a clinical context." (PMID 26158630, 2015). "EphA2 has been correlated with cancer cell survival, and some previous studies have reported that therapeutic targeting of EphA2 is effective for some cancers." (PMID 26516928, 2015). "As a receptor tyrosine kinase overexpressed in a variety of human cancers, EPHA2 has been extensively studied and represents a novel drug target for cancer therapeutics." (PMID 25577646, 2015). "Phase I and II clinical therapeutic trials have been evaluated using siRNAs to inhibit critical cancer-associated genes, including siRNA-EphA2-DOPC (targeting EphA2), TKM-080301 (targeting PLK1), and CALAA-01 (targeting RRM2)." (PMID 26448935, 2015). "We found double-positive samples in various cancers except for one stomach sample exhibiting pS-EphA2 positivity and pRSK negativity, suggesting a strong signalling correlation between EphA2 and RSK in human cancer tissues." (PMID 26158630, 2015). "Eph genes, including EphA2, have in some cases been shown to be over-expressed in cancer and to have a positive oncogenic effect." (PMID 26083390, 2015). "A previous study demonstrated that EphA2 regulates the growth of cancer cells via numerous signalling pathways, reflecting its complicated regulatory network." (PMID 25351620, 2015). "Predicted HFI SNVs were not distributed evenly across disease subsets; SNVs in ULK4, BMP2K, PALB2, ALPK3 were more frequent in triple negative cancers (TNBC) whereas SNVs in EPHA2 was more common in ER positive cancers." (PMID 26420498, 2015). "Although ephrinA1 is expressed at low levels in cancer cells it can robustly activate EphA2 upon release into the extracellular environment." (PMID 25344320, 2014). "In conclusion, we developed a capsid-modified Ad vector, Ad5T/41sSK-IJ-YSA, targeted to cancer cells in vitro and in vivo by using the pan-cancer marker EphA2 as receptor for virus entry." (PMID 24760010, 2014). "Ad5T/41sSK-IJ-YSA offers interesting opportunities for applications in gene therapy and virotherapy of several cancers reported to overexpress EphA2." (PMID 24760010, 2014). "After 6 days, control siRNA-treated cells migrated out of the cancer cell mass into the surrounding collagen gel but EphA2/EphA4 knockdown cells displayed significantly less invasion." (PMID 24795148, 2014). "In the literature, EphA2 signaling in epithelial and cancer cells can induce morphological changes reminiscent of transition between epithelial and mesenchymal states." (PMID 24606764, 2014). "Consistent with the finding that CIL drives embryonic cell dispersal during development, we show here that EphA receptors mediate CIL via Vav2 and RhoA and that EphA2/EphA4 can regulate cancer cell dissemination from dense cancer cell populations." (PMID 24795148, 2014).
cancer (continued). "Our findings are consistent with a recent study showing that MT1-MMP cleavage of EphA2 can enhance individual cancer cell invasion via RhoA-mediated repulsive signalling." (PMID 24795148, 2014). "Despite the results of this study, EphA2 remains a potential target for cancer therapeutics, because it is overexpressed in a number of cancer types, and this is correlated with poor patient outcome." (PMID 22370972, 2013). "The results observed so far with some of these therapeutic approaches support EphA2 as a cancer target." (PMID 22370972, 2013). "Here we show that in cancer cells, coexpressed ephrin-A3 can inhibit the ability of EphA2 and EphA3 to bind ephrins in trans and become activated, while ephrin-B2 can inhibit not only EphB4 but also EphA3." (PMID 24348920, 2013). "In the present study, EphA2, ephrinA1, and even EphA4 were also expressed in vascular endothelial cells existing in cancer tissue." (PMID 23738943, 2013). "The antibody has no antitumor effects when unconjugated; thus, it was intended to be used to deliver highly toxic chemotherapy directly to EphA2-expressing cancer cells." (PMID 22370972, 2013). "Previous studies on ephrin-A1 in NSCLC have been conflicting, as associations to improved patient outcome have been reported, while upregulation of the ephrin-A1 receptor EphA2 has also been related to poor clinical outcomes in many types of cancer." (PMID 24215488, 2013). "Among the Eph receptors, EphA2 and EphB4 are the most widely expressed in epithelial and cancer cells, although most other Eph receptors including EphA3 are also aberrantly expressed in at least some cancers." (PMID 24348920, 2013). "The expression of ephrinA1, known to be a major ligand of EphA2, has been studied in various cancers." (PMID 23738943, 2013). "Subsequent studies revealed that EphA2 was overexpressed in human cancers, and that overexpression was correlated with malignant progression and poor prognosis." (PMID 22916121, 2012). "Mechanistically, EphA2 is found to be a substrate of Akt that is activated in different human cancers." (PMID 22916121, 2012). "The reduction in EphA2 was both dose and time dependent, confirming that in KS, as in other cancers, EphA2 is a client of Hsp90." (PMID 23209418, 2012). "Among allEph receptors, EphA2 is the most widely studied in oncology field because of itsexpression and function in several cancer types." (PMID 21479221, 2011). "It has been reported that knockdown of EphA2 in cancer cells inhibited cell malignancy and invasion." (PMID 21264258, 2011). "We conclude that the ability of cancer cells to release EFNA1 is an important step in EPHA2-mediated transformation in a subset of cancer cells." (PMID 20979646, 2010). "In cancers, ligand expression is downregulated during the malignant process, leading to constitutive EphA2 signaling." (PMID 20628489, 2010). "Soluble EFNA1 is important for the growth of two cancer cell lines and contributes to the relocalization of EPHA2 away from cell-cell contacts which accompanies transformation." (PMID 20979646, 2010). "EphA2 agonistic antibodies are thought to function by restoring a signal that is normally provided by receptor-ligand binding but is lost in most cancer cells due to poor receptor-ligand interactions." (PMID 20130824, 2009). "EphA2 is over-expressed in different types of cancer including pancreatic, lung, melanoma, colorectal, ovarian, and breast." (PMID 20130824, 2009). "Various strategies have been proposed to target EphA2 in cancer, including the use of monoclonal antibodies directed at EphA2 surface antigens and RNAi to EphA2." (PMID 18797457, 2008). "For example, high levels of EphA2 have been documented in metastatic melanoma, as well as cancers of the mammary gland, cervix, ovary, prostate, colon, lung, kidney, esophagus and pancreas." (PMID 18797457, 2008). "Ephrin A5 does not bind significantly to EphA1 but has been shown to activate EphA2 in human carcinoma cells." (PMID 16737551, 2006).